CXCL10 (C-X-C motif chemokine ligand 10)
Diseases named in the same sentence as CXCL10 in open-access papers (continued):
Sharing a sentence is not in itself a finding about the gene and the disease.
kidney disease (23 papers, 2018 to 2025). "High expressions of chemokines and their receptors in the infiltrating immune cells are recognized as the characteristic events in the progression of DN and CXCR3, and its ligands, CXCL9, CXCL10, and CXCL10 are the well-known risk factors for inflammatory-based kidney diseases." (PMID 36686486, 2022). "Colony-stimulating factor 1 (Csf1) and C-X-C motif chemokine ligand 10 (Cxcl10) are expressed in renal epithelial cells and play crucial roles in producing and infiltrating inflammatory cells, thereby contributing to kidney disease development." (PMID 40516868, 2025). "In the last few years, several studies have indicated that C-X-C motif chemokine 10 (CXCL10) is involved in developing renal diseases." (PMID 38611630, 2024). "CXCL13 promoted the proliferation of human renal MCs, and CXCL10 overexpression correlated with clinical LN and showed utility as a new marker to assess renal disease activity in Chinese patients with pediatric SLE." (PMID 38762508, 2024). "Different studies have indicated that C-X-C motif chemokine 10 (CXCL10) is involved in developing renal diseases through the chemoattraction of inflammatory cells and facilitating cell growth and angiostatic effects." (PMID 38611630, 2024). "Due to the role of CXCL-10 in the body, it has been found that it can be used for the noninvasive diagnosis of kidney disease." (PMID 35669103, 2022). "In the last few years, strong experimental and clinical evidence has indicated that CXCL10 is involved in the development of renal diseases through the chemoattraction of inflammatory cells and facilitation of cell growth and angiostatic effects." (PMID 32089645, 2020). "Nonetheless, the specific function of CXCL10 in different renal diseases is still unclear, and interactions between chemokines and specific cell types in the pathogenesis of various renal diseases must be investigated." (PMID 32089645, 2020). "The aim of this review is to summarize the current understanding of the role of CXCL10 in various renal diseases, mainly focusing on the mechanism elucidated in both experimental and clinical studies." (PMID 32089645, 2020). "Thus, CXCL10 appears to be involved in the recruitment of macrophages to the myocardium and cardiac phenotypical response during kidney disease." (PMID 35090403, 2022). "In this review, the role of CXCL10 in different renal disease models will be highlighted." (PMID 32089645, 2020). "CXCL10 is known to be highly expressed during kidney disease." (PMID 32977372, 2020). "In this review, we summarize the structures and biological functions of CXCL10 and CXCR3, focusing on the important role of CXCL10 in the pathogenesis of kidney disease, and provide a theoretical basis for CXCL10 as a potential biomarker and therapeutic target in human kidney disease." (PMID 32089645, 2020). "Indeed, the chemokine CXCL10 may be a novel therapeutic target and potential biomarker for renal diseases." (PMID 32089645, 2020). "Non-invasive biomarkers of renal disease such as chemokines (e.g., CXCL9, CXCL10) and donor-derived cell-free DNA are increasingly being considered to improve diagnosis and predict allograft rejection." (PMID 38916313, 2024). "CXCL10/CXCR3 expression was analyzed in two experimental models of nephrotic syndrome, puromycin aminonucleoside nephropathy (PAN) and anti-nephrin antibody-induced nephropathy (ANA), both with slit diaphragm (SD) dysfunction resulting in proteinuria." (PMID 32089645, 2020). "Elevated CXCL10 and CXCR3 levels were detected in various renal diseases and correlated with disease progression." (PMID 32089645, 2020). "As a further step towards translating our findings into human disease, we examined plasma expression of CXCL10 in patients (n = 37) with CKD stages 3–5, (based on the Kidney Disease Outcomes Quality Initiative guidelines) and compared to healthy controls (n = 24)." (PMID 35090403, 2022).
kidney disease (continued). "Though CXCL10 and EGF have been reported altered in a variety of renal diseases, even in the kidney rejection, the network of CXCL10, EGF and STAT1 in BKVN has not been reported." (PMID 29567951, 2018).
adenocarcinoma (13 papers, 2012 to 2023). A common cancer characterized by the presence of malignant glandular cells. "It was more potent than CXCL10 in the adenocarcinoma model, but showed equal potency compared to CXCL9 in the LLC model." (PMID 34503058, 2021). "CT26-CXCL10 cells (expressing CXCL10) were unable to form tumors in immune-competent hosts, whereas control cells gave rise to poorly differentiated adenocarcinomas with high cellularity, extended areas of necrosis, and abundant mitoses." (PMID 29163806, 2017). "Furthermore, reduced CXCL10 levels are associated with poor prognosis, and restoration of CXCL10 in the human adenocarcinoma cell line A549 led to inhibition of tumorigenesis without increased leukocyte infiltration." (PMID 36164329, 2022). "In agreement with studies carried out in adenocarcinoma cell lines, we found similar upregulation of genes such as IDO1, GBP1, CXCL9, CXCL10, and CXCL11 in response to IFN-γ, all of which are also known to be upregulated in IBD patients." (PMID 33396621, 2020). "Additionally, in comparison with normal samples, the expression level of CCR7, CXCL10, IDO1, and MMP9 were increased in phases of adenocarcinoma’s tissue, while the expression level of CXCL9 and VCAM1 were decreased." (PMID 31214045, 2019).
neurodegenerative disease (13 papers, 2013 to 2024). A disorder of the central nervous system characterized by gradual and progressive loss of neural tissue and neurologic function. "Among mRNAs with the same expression pattern in the maternal and infant groups, CXCL10 was overexpressed, confirming the suppression of neurogenesis or involvement in various neurodegenerative diseases." (PMID 38892402, 2024). "It is known that Cxcl10 has a role in the recruitment of inflammatory cells and neurodegenerative diseases." (PMID 36291747, 2022). "In line with what has been found in several neurodegenerative diseases, many of these inflammatory mediators were found differentially regulated in our study, including CXCL10, a chemokine shown to induce apoptosis in fetal neurons." (PMID 28861067, 2017). "The expression of CXCL10 or interferon gamma-induced protein 10 (IP-10) has been observed during several neurodegenerative diseases and plays a crucial role in T-cell-mediated inflammation in the CNS46." (PMID 28747667, 2017). "Interestingly, genes associated with the recently characterized neurodegenerative disease-associated phenotype (DAM microglia), such as Clec7a, Csf1, Cd74, Cxcl10 and Cybb, were downregulated in 5xFAD/Gal3KO mice compared to 5xFAD mice." (PMID 31006066, 2019). "CXCL10, a member of the CXC chemokine family, can also attract bone marrow-derived mesenchymal stem cells (BM-MSCs), and CXCL10-expressing cells appear in the inflamed central nervous system after a trauma or in neurodegenerative diseases." (PMID 28698717, 2017).
respiratory diseases (13 papers, 2007 to 2025). "CXCL9, CCL2, IL6, CXCL10, and IL8 have been linked to various respiratory diseases and retain sensitivity for their level estimates as well." (PMID 40650062, 2025). "In multiple animal models of respiratory diseases, the treatment with XC221GI led to controlling the levels of CXCL9, CXCL10, CXCL11, IL-6 and IL-8, and to decrease of extent of the pathogen-driven cytokine storm." (PMID 37214455, 2023). "Expression levels for CXCL10 and IFNG were 4.8 and 2.6 times higher, respectively, in the vaccinated animals, most likely due to two animals with mild symptoms of non-respiratory disease in the vaccinated group." (PMID 35062765, 2022).
metabolic disorders (10 papers, 2019 to 2025). "We speculate that studying the synergistic interactions among such inflammatory triggers for CXCL10 induction/upregulation in major immune effectors would be another interesting scenario, given the emerging pathophysiological significance of these inflammatory proteins in metabolic disorders." (PMID 39065674, 2024).
inflammatory myopathies (8 papers, 2014 to 2023). "Upregulation of CXCL10 is also linked to the development of inflammatory myopathies." (PMID 34212132, 2021). "CXCL10 is also reportedly involved in pathological muscle conditions, such as inflammatory myopathies, suggesting that it serves as a potential therapeutic target for these conditions." (PMID 37152289, 2023). "CXCL10 is involved in inflammatory diseases, and in inflammatory myopathies, and CXCL10 levels rise in response to muscle damage." (PMID 34078750, 2021). "While CXCL10 is predominantly associated with a Th1 response, it has been recently identified in inflammatory myopathies, and secretion of CXCL10 from human fetal skeletal muscle cells is induced by treatment with either interferon (IFN)-γ or TNFα." (PMID 26856410, 2016).
cardiac disease (7 papers, 2016 to 2026). "Interestingly, C-X-C Motif Chemokine Ligand 10 (Cxcl10), and CxCl11 proteins were both upregulated in patients with heart disease and some studies indicate this is true for DOX cardiotoxicity as well." (PMID 32960902, 2020). "The purpose of this study is to verify whether sildenafil could target CXCL10 in human cardiomyocytes challenged by Th1-type-inflammatory stimuli; IL-6 and IL-8, both involved in inflammation and cell damage in cardiac disease, have been also investigated." (PMID 27165639, 2016). "Higher CXCL10 and CXCL8 levels detected in patients with different cardiac diseases vs. healthy subjects likely reflect early inflammatory processes, differently from classical biomarkers, which reveal already established damages." (PMID 39355618, 2024). "In particular, previous human in vivo and in vitro studies reported that CXCL10, released by cardiac, endothelial and immune cells challenged by inflammatory conditions could be eligible as reliable marker and therapeutic target at early stages of heart disease, when Th1-type dominance prevails." (PMID 27165639, 2016). "The main finding of this study is that sildenafil in human cardiomyocytes inhibited protein and gene expression of IFNγ + TNFα-induced chemokine CXCL10 (IC50 2.6 × 10−7 M), which is a critical trigger of early Th1 immune/inflammatory response during cardiac diseases." (PMID 27165639, 2016). "This is the case of the chemokines CXCL10 and CXCL8, classified as ERL- and ERL+, based on absence or presence of Glut-Leu-Arg motif, both molecules with multifaceted functions in disease development, widely engaged in cardiac disease initiation and progression." (PMID 39355618, 2024).
hematological malignancies (5 papers, 2018 to 2025). "Patients with hematological malignancies showing diminished systemic cytokine response (IFN-γ, IL-15 and CXCL10/IP-10) also had correlating but lower anti-Spike antibody levels." (PMID 38090597, 2023). "In contrast to vaccination of a cohort of healthy participants, patients with hematological malignancies who had a lower anti-Spike response, also had a diminished systemic cytokine response (IFN-γ, IL-15 and CXCL10/IP-10), and this correlated with the lower anti-Spike antibody levels." (PMID 38090597, 2023). "In conclusion, in patients with hematological malignancies who underwent cell therapies, the ability to acutely upregulate IFN-γ and IP-10/CXCL10 at the priming vaccination and IFN-γ, IL-15, IL-7 and IL-10 upon booster vaccination were predictive of successful Ab development." (PMID 35693807, 2022). "For example, in patients with hematological malignancies who failed to produce anti-SARS-CoV antibodies, the innate systemic response was primarily characterized by IL-8 and MIP-1α, with a significant reduction in the IFN-γ, IL-15, and IP-10/CXCL10 response." (PMID 40160814, 2025).
vasculopathy (5 papers, 2013 to 2025). "Among CXC chemokines, CXCL10 is known to contribute to SSc-associated vasculopathy, through the interaction with the specific receptor subtype." (PMID 36077548, 2022). "This property may reflect its ability to inhibit CXCL10, a known, early contributor to SSc-associated vasculopathy, effectively preventing activation of endothelial cells and dermal fibroblasts in patients with SSc." (PMID 36847929, 2023). "The results indicate that CXCL10 induces apoptosis in HBVECs and neuroglia cells in a dose-dependent manner suggesting that increased levels of CXCL10 in CM patients may play a role in vasculopathy, neuropathogenesis, and brain injury during CM pathogenesis." (PMID 23630573, 2013).
gastrointestinal tumors (3 papers, 2022 to 2026). "Preliminary experiments with CNBs from lung, kidney, and gastrointestinal tumors revealed cytokine induction patterns unique to individual specimens, particularly in IFNγ and CXCL10." (PMID 40791544, 2025).
head and neck tumor (2 papers, 2025 to 2026). "Longitudinal, cumulative concentration assessment of CXCL10 and IFNγ from a representative human head and neck tumor resection showed an increased production rate with αCD3/αCD28 stimulation for both cross-well and sequential treatment experiments." (PMID 40791544, 2025).
central nervous system diseases (1 paper, 2023). "Previous studies have shown that the NF‐ĸB pathway is a classical signaling pathway involved in CXCL10 synthesis in different central nervous system diseases and injury models." (PMID 37475184, 2023).
CXCL10 also shares sentences with these, for which no sentence is quoted: viral diseases (10 papers); basal cell carcinoma (8); macular edema (8); multiple myeloma (8); scleroderma (8); periodontal disease (7); viral meningitis (7); bacterial vaginosis (6); cystic fibrosis (6); Dengue hemorrhagic fever (6); Kawasaki disease (6); Parkinson disease (6); Cachexia (5); head and neck squamous cell carcinoma (5); kidney (5); sarcopenia (5); acute myeloid leukemia (4); bronchitis (4); CNS tumors (4); coagulopathy (4); diabetic macular edema (4); diabetic nephropathy (4); Encephalopathy (4); falciparum malaria (4); glomerular diseases (4); Hypercholesterolemia (4); infarction (4); Japanese encephalitis (4); portal hypertension (4); pulmonary edema (4).
A further 309 diseases each share a sentence with CXCL10 in 4 papers or fewer.